TPSD1 (tryptase delta 1)
Description:
Tryptase is the major neutral protease present in mast cells and is secreted upon the coupled activation-degranulation response of this cell type.
Synonyms: MCP7-LIKE; MCP7L1; MMCP-7L
Tractability: Small molecule: a high-quality ligand is known. Antibody: UniProt places it where antibodies can reach, with medium confidence; UniProt predicts a signal peptide or a membrane-spanning region; its Gene Ontology location is reachable by antibodies, with medium confidence. PROTAC: a small molecule that binds it is known.
Gene: Protein-coding gene on chromosome 16 (1,256,059 to 1,259,008, forward strand). Ensembl gene ENSG00000095917.
Subcellular location: Secreted
Gene Ontology:
Molecular function: serine-type endopeptidase activity; serine-type peptidase activity; peptidase activity
Biological process: proteolysis
Cellular component: extracellular region
Genetic constraint (gnomAD): Loss-of-function variants: 30 observed, 23.02 expected, observed/expected ratio (o/e) 1.3, 90% interval 0.97 to 1.75. The synonymous counts are far from expectation, so gnomAD's model fits this gene poorly and the ratio says little. Missense variants: 420 observed, 303.64 expected, observed/expected ratio (o/e) 1.38, 90% interval 1.28 to 1.5. Synonymous variants: 176 observed, 138.4 expected, observed/expected ratio (o/e) 1.27, 90% interval 1.12 to 1.44.
Homologues: Orthologues: macaque TPSD1 (89% identical), zebrafish prss60.1 (38% identical), zebrafish zgc:165423 (38% identical), Drosophila melanogaster flz (37% identical), zebrafish prss60.2 (36% identical), zebrafish si:dkey-16l2.17 (36% identical), zebrafish prss60.3 (35% identical), zebrafish zgc:123295 (35% identical), tropical clawed frog tpsg1 (34% identical), tropical clawed frog prss27.3 (33% identical), zebrafish si:dkeyp-93a5.2 (33% identical), zebrafish zgc:153968 (33% identical), and 45 more. Paralogues in human: TPSAB1 (83% identical), TPSB2 (82% identical), TPSG1 (41% identical).
Diseases named in the same sentence as TPSD1 in open-access papers:
TPSD1 is named in the same sentence as 8 diseases in open-access papers, as found by Europe PMC text mining. Sharing a sentence is not in itself a finding about the gene and the disease. The quoted sentences say what the papers report.
colon cancer (2 papers, 2022 to 2024). "A specific mutation in TPSD1 was observed in colon cancer patients who did not respond well to chemotherapy." (PMID 38287071, 2024). "A particular mutation of TPSD1 p.Ala92Thr was observed in colon cancer among those non-responders after 5-fluorouracil-based therapy." (PMID 35831825, 2022).
breast carcinoma (1 paper, 2025). "Among the key genes found in these enriched categories, TPSD1, FABP4, CARTPT, TRH, CSN3, and MMP9 stand out based on previously published data, which suggest their critical roles in cancer progression, including breast cancer." (PMID 40870889, 2025).
rotator cuff tear (1 paper, 2023). "Increased TPSD1 expression was also observed in patients with regenerative rotator cuff tear." (PMID 37511292, 2023).
urticaria (1 paper, 2023). A vascular reaction of the skin characterized by erythema and wheal formation due to localized increase of vascular permeability. "The urticaria-associated variant rs4410077[T] at TPSD1, does not correlate with a reported copy number of TPSAB1 (r2 = 0.011)." (PMID 37430141, 2023).
respiratory disease (1 paper, 2023). "For example, TPSD1 expression was increased in patients with aspirin-exacerbated respiratory disease." (PMID 37511292, 2023).
TPSD1 also shares sentences with these, for which no sentence is quoted: cancer (1 paper); Hip Osteoarthritis (1); tumor (1).